RN7SL294P (RNA, 7SL, cytoplasmic 294, pseudogene)
Gene: Miscellaneous RNA gene on chromosome 3 (75,182,754 to 75,183,048, reverse strand). Ensembl gene ENSG00000242638.
Homologues: Orthologues: chimpanzee Metazoa_SRP (98% identical), macaque Metazoa_SRP (92% identical). Paralogues in human: RN7SL1 (82% identical), RN7SL2 (81% identical), RN7SL3 (80% identical), RN7SL655P (80% identical), RN7SL296P (80% identical), RN7SL122P (79% identical), RN7SL125P (79% identical), RN7SL127P (79% identical), RN7SL220P (78% identical), RN7SL597P (78% identical), RN7SL660P (78% identical), RN7SL709P (78% identical), and 703 more.